PINK1 (PTEN induced kinase 1)
Diseases named in the same sentence as PINK1 in open-access papers (continued):
Sharing a sentence is not in itself a finding about the gene and the disease.
nonalcoholic fatty liver (1 paper, 2019). "In an animal model of high-fat diet–induced nonalcoholic fatty liver, the results have indicated that impaired PINK1/Parkin-dependent mitophagy may be responsible for hepatic fatty acid accumulation." (PMID 31649547, 2019). "As expected, quercetin, a common flavonoid, can activate PINK1/Parkin-mediated mitophagy to accelerate mitochondrial fatty acid oxidation and inhibit hepatic fatty acid accumulation in an animal model of high-fat diet–induced nonalcoholic fatty liver." (PMID 31649547, 2019).
obliterative bronchiolitis (1 paper, 2021). "Our study showed that APN suppressed proinflammatory factors (TNF-α and IL-6) through SIRT1- PINK1 signaling-mediated mitophagy, leading to inhibition of lung IR injury, which might mitigate the subsequent occurrence of acute graft rejection and obliterative bronchiolitis." (PMID 34602075, 2021).
Osteopenia (1 paper, 2023). Osteopenia is a term to define bone density that is not normal but also not as low as osteoporosis. "In conclusion, by in vivo and in vitro studies, we found that PINK1/Parkin-mediated mitophagy could inhibit AOPP-induced osteoblast apoptosis by eliminating damaged mitochondria and scavenging ROS, thus inhibiting osteopenia and bone microstructural destruction." (PMID 36750550, 2023).
parasite infection (1 paper, 2024). "As expected, knockdown of PINK1 significantly induced ROS generation and inhibited parasite infection." (PMID 39405338, 2024).
Parkinson disease 6 (1 paper, 2019). A neurodegenerative disorder characterized by parkinsonian signs such as rigidity, resting tremor and bradykinesia. "PINK1 and Parkin are causal gene products for recessive familial Parkinsonism PARK6 (Parkinson disease 6) and AR-JP (autosomal recessive juvenile parkinsonism, also called PARK2), respectively." (PMID 31110043, 2019).
Postural instability (1 paper, 2017). A tendency to fall or the inability to keep oneself from falling; imbalance. "Also, for the patient with the PINK1 stop mutation, postural instability was not seen after 20 years of disease duration." (PMID 29163333, 2017).
preeclampsia (1 paper, 2018). Preeclampsia is a hypertensive disorder of pregnancy that is characterized by new-onset hypertension with proteinuria presenting after 20 weeks of gestation, and depending on mild or severe forms may initially present with severe headache, visual disturbances, and hyperreflexia. "Moreover, we found that full-length PTEN-induced putative kinase 1 (PINK1) and Parkin, were elevated in mitochondria from PE placentae, implicating mitophagy as the process that degrades excess mitochondria fragments produced from CER/BOK-induced fission in preeclampsia." (PMID 29463805, 2018).
prostate adenocarcinoma (1 paper, 2025). "In prostate adenocarcinoma (PRAD), OPTN, PRKN, BNIP3L, PINK1, and MAP1LC3A were significantly downregulated." (PMID 39859167, 2025).
psychological distress (1 paper, 2020). "Our study suggests that PINK1 is indispensable for maintaining proper mitochondrial metabolism in PBMCs and profiling the bioenergetics in PBMCs may be used as a proxy to inform on: 1) the progression of PD pathology and, 2) oxidative stress induced by psychological distress and by PINK1 deficiency." (PMID 32555260, 2020). "We surmised that PINK1 modulates the bioenergetics of peripheral blood mononuclear cells (PBMCs) under basal conditions or in situations that promote oxidative stress as psychological distress." (PMID 32555260, 2020). "Nonetheless, this study paves the way for performing additional experiments to gain more knowledge on specific redox species produced by PBMCs from WT vs. PINK1-KO animals exposed to psychological distress." (PMID 32555260, 2020). "The level of antioxidant markers and brain-derived neurotrophic factor were altered in PINK1-KO-PBMCs and by psychological distress." (PMID 32555260, 2020). "In summary, our data suggest that PINK1 is critical for modulating the bioenergetics and antioxidant responses in PBMCs whereas lack of PINK1 upregulates compensatory glycolysis in response to oxidative stress induced by psychological distress." (PMID 32555260, 2020). "In addition, the bioenergetic alterations in PBMCs coincided with the onset of motor symptoms in the same cohort of PINK1-KO and WT rats that were untreated or exposed to psychological distress." (PMID 32555260, 2020). "PBMCs derived from stressed animals exhibited an over-reliance on glycolysis to compensate for possible mitochondrial dysfunction caused by a lack of PINK1 and by psychological distress." (PMID 32555260, 2020). "The present study sheds light on the vital role that PINK1 plays in modulating the bioenergetic state of PBMCs under physiological conditions and under pathological conditions in the context of oxidative stress induced by psychological distress and in a rat model of PD3." (PMID 32555260, 2020). "Therefore, our data suggest that psychological distress stimulates glycolysis and concomitantly decreases OXPHOS in a larger pool of mitochondria in PINK1-KO-PBMCs." (PMID 32555260, 2020). "Consistent with its role in maintaining mitochondrial structure/function, our data suggest that the lack of PINK1, but not exposure to psychological distress, augments OXPHOS and glycolysis in PBMCs." (PMID 32555260, 2020). "However, psychological distress did not significantly change the overall bioenergetic state of WT-PBMCs whereas PINK1-KO cells exhibited an increase in glycolytic capacity." (PMID 32555260, 2020). "In addition, psychological distress enhanced the glycolytic capacity in PINK1-KO-PBMCs but not in WT-PBMCs." (PMID 32555260, 2020). "However, when mitochondria are treated with respiratory uncouplers (max OCAR/ECAR ratio), stressed PINK1-KO cells modestly shifted from OXPHOS to glycolysis, suggesting that depletion of PINK1 decreases the mitochondrion efficiency during oxidative stress elicited by psychological distress." (PMID 32555260, 2020). "However, psychological distress did not further shift the baseline OCRs or ECARs in PINK1-KO-PBMCs." (PMID 32555260, 2020). "Interestingly, psychological distress did not disrupt the energy metabolism in WT-PBMCs, but it enhanced the glycolytic capacity in PINK1-KO-PBMCs (p = 0.052), suggesting that long-term distress alters the mitochondrial metabolism while concomitantly enhancing glycolysis in PINK1-KO-PBMCs." (PMID 32555260, 2020). "On the other hand, psychological distress did not alter BDNF level in both WT and PINK1-KO cells." (PMID 32555260, 2020). "While exposure to psychological distress did not have an additive effect on their OXPHOS status, PBMCs derived from PINK-KO rats (PINK1-KO-PBMCs) underwent significant metabolic switching from OXPHOS to glycolysis in response to oxidative stress induced by psychological distress." (PMID 32555260, 2020).
pulmonary edema (1 paper, 2024). Accumulation of fluid in the lung tissues causing disturbance of the gas exchange that may lead to respiratory failure. "For instance, low doses of caffeine may serve as a therapeutic option for treating High Altitude Pulmonary Edema (HAPE) by promoting PINK1/parkin‐dependent mitophagy and mitochondrial fission in Type I alveolar epithelial cells, thereby improving mitochondrial quality control." (PMID 39670604, 2024).
REM sleep behavior disorder (1 paper, 2025). A disorder characterized by episodes of vigorous and often violent motor activity during rem sleep (sleep, rem). "Here, we investigated T cell responses towards PINK1 and α-syn in donors at high risk of developing PD (i.e. prodromal PD: genetic risk, hyposmia, and or REM sleep behavior disorder), in comparison to PD and healthy control donors." (PMID 40419563, 2025).
seborrheic dermatitis (1 paper, 2024). A chronic, inflammatory skin disorder that affects the scalp, central face and skin folds; it is characterized by scaling and itching. "For instance, the association of seborrheic dermatitis with PD may originate from the shared genetic polymorphisms of GBA, LRRK2, and PINK1, which play a role in immune changes, lipid metabolism, and homeostasis of brain." (PMID 38468488, 2024).
spina bifida aperta (1 paper, 2023). "Similarly, mitophagy was also found to be impaired in a rat model of spina bifida aperta, accompanied by downregulating the expression of LC3II/LC3I and PINK1." (PMID 37629033, 2023).
Streptococcus infection (1 paper, 2023). "Similarly, PINK1 and Parkin-mediated mitophagy have been shown to prevent Streptococcus infection-induced lung damage by downregulating inflammasome activation and promoting apoptosis." (PMID 37153108, 2023).
teratoma (1 paper, 2016). A non-seminomatous germ cell tumor characterized by the presence of various tissues which correspond to the different germinal layers (endoderm, mesoderm, and ectoderm). "Conversely, PINK1−/−-iPSCs developed teratomas consisting almost exclusively of fully committed adult tissues, forming very small, morpho-logically benign, mature, and well-differentiated cystic lesions." (PMID 27295498, 2016). "Despite the lower efficiency in teratoma formation and the longer latency, tissue composition of PINK1−/−-teratomas was not noticeably different from equivalent PINK+/+-teratomas at the histological level." (PMID 27295498, 2016).
triple-negative breast carcinoma (1 paper, 2022). An invasive breast carcinoma which is negative for expression of estrogen receptor (ER), progesterone receptor (PR), and human epidermal growth factor receptor 2 (HER2). "It has been reported that phosphorylation of Drp1 at S616 by Pink1 induces mitophagy-independent mitochondrial fission in somatic HEK293 cells, and Redox oxidative species (ROS)-mediated phosphorylation of Drp1S616 promotes mitochondrial fission in triple-negative breast cancer cells." (PMID 35410319, 2022).
type 1 diabetes (1 paper, 2017). "In a rat model of type 1 diabetes, PINK1 protein expression was increased in the renal cortex after 4 weeks of STZ injection." (PMID 28767702, 2017).
uterine cancer (1 paper, 2023). Primary or metastatic malignant neoplasm involving the uterine corpus and/or the cervix. "According to data from The Cancer Genome Atlas (TCGA), high expression of PINK1 was associated with a better prognosis for renal and uterine cancers." (PMID 36830954, 2023).
uterine corpus endometrial carcinoma (1 paper, 2020). A endometrial carcinoma (disease) that involves the body of uterus. "Furthermore, PINK1 was newly identified as a detrimental prognostic factor for both OS and RFS in UCEC (uterine corpus endometrial carcinoma) (OS: log rank P = 4.7e-05; RFS: log rank P = 0.046)." (PMID 33244455, 2020).
Venous thrombosis (1 paper, 2024). Formation of a blood clot (thrombus) inside a vein, causing the obstruction of blood flow. "Platelet-lymphocyte aggregates are associated with increased thrombosis risk, and venous thrombosis is a cause of sudden death in PD, suggesting targeting the Pink1/Parkin pathway in the periphery has therapeutic potential." (PMID 38854001, 2024).
young-onset Parkinson disease (1 paper, 2025). A form of Parkinson disease (PD) characterized by an age of onset between 21-45 years, rigidity, painful cramps followed by tremor, bradykinesia, dystonia, gait complaints and falls, and other non-motor symptoms. "This is a highly regulated process, and mutations in genes encoding both PINK1 and Parkin have been associated with familial forms of young-onset Parkinson’s disease (YOPD) as well as other human diseases." (PMID 39909370, 2025).
ZIKV infection (1 paper, 2023). "ZIKV infection upregulated mitochondrial expression levels of BNIP3, NIX, and PINK1." (PMID 37781396, 2023).
Zinc deficiency (1 paper, 2024). A deficiency of the essential metal Zinc; an essential cofactor for many enzymes. "Our findings demonstrated a significant increase in the levels of PINK1 and PARKIN proteins in the ovaries of mice with zinc deficiency, indicative of mitophagy induction." (PMID 38807213, 2024).
cancer (158 papers, 2010 to 2026). A tumor composed of atypical neoplastic, often pleomorphic cells that invade other tissues. "Downregulation of PINK1/Parkin- or Rab9a-mediated mitophagy has been linked to increased radiosensitivity and chemosensitivity in cancer cells." (PMID 40750884, 2025). "Dysregulation of mitophagy has been implicated in cancer, with PINK1 playing a dual role, depending on the cellular context." (PMID 40243539, 2025). "The distinctive contribution of this study lies in its examination of genetic forms of PD—including carriers of LRRK2, GBA1, SNCA, PRKN, and PINK1 mutations—in relation to cancer risk." (PMID 41300754, 2025). "Mitophagy is a critical cellular pathway regulated by Parkin and PINK1 that is involved in numerous processes, including cancer, immunity, and tissue loss." (PMID 40305785, 2025). "On the other hand, PINK1 has some protective effects against some types of cancer, and its loss results in elevated proliferation of glioma cells, decreased oxygen consumption, and raised glycolysis." (PMID 38612708, 2024). "Specifically in cancer cells, PINK1 has previously been implicated not only in mitochondrial homeostasis but also in areas including cell-cycle progression, apoptosis, and chemotherapeutic efficacy." (PMID 39440945, 2024). "The loss of PINK1 and Parkin activity, observed in various cancers, has been associated with cancer progression and metastasis." (PMID 39596452, 2024). "Considering the implications in other cancer types regarding PINK1 and its positive association with mitochondrial activity and chemoresistance across multiple drug classes, the need for an examination in our specific model is evident." (PMID 39440945, 2024). "HBx is a major cause of HBV-related cancer, and the thyroid protects hepatocytes from HBx-induced ROS damage and carcinogenesis by triggering selective mitophagy through the activation of the PINK1/Parkin pathway." (PMID 38299199, 2024). "Deficiency of PINK1 promotes the Warburg effect and cancer progression by regulating mitophagy, metabolic reprogramming, and tumor-associated macrophagy (TAM) polarization." (PMID 36831455, 2023). "Previous studies have shown that PINK1 deficiency promotes the Warburg effect and cancer progression by regulating mitophagy, cancer metabolic reprogramming, and tumor-associated macrophage polarization in gastric cancer." (PMID 36831455, 2023). "Several studies have linked PINK1 to cancer but its involvement in carcinogenesis is complex and context-dependent, and both pro- and anti-tumorigenic effects of PINK1 have been reported." (PMID 35600352, 2022). "Because of the central role of PINK1 in mitochondrial function and dynamics, and to further explore the function of PINK1 in cancer, we studied the consequences of PINK1 loss on the growth of oncogenic Ras-driven tumors." (PMID 35600352, 2022). "Research over the past decade has shown that PINK1 is implicated in various cellular functions such as cell survival, stress resistance, and mitochondrial homeostasis in cancer cells." (PMID 33912571, 2021). "The association between PINK1 copy number variations and immune infiltrates in different kinds of cancer was investigated." (PMID 33244455, 2020). "PINK1 mutations occur in some of cancers, while PINK1 expression is increased in some cancer tissues and decreased in others." (PMID 30595797, 2018). "PINK1 was also recently discovered to regulate the cell cycle, which underlines its potential as an anti-cancer therapeutic focus." (PMID 30344951, 2018). "This new function of PINK1 as a regulator of the cell cycle draws attention to the function of PINK1, via mitochondrial quality control, in both cell division, and cell differentiation programs, that underlie cancer and adult neuronal phenotypes." (PMID 26973853, 2016). "Complementing previous work on Parkin and cancer, recent studies have now linked PINK1 with both cancer and metabolism." (PMID 25345844, 2015).
cancer (continued). "PTEN regulates the function of PTEN induced putative kinase 1 (PINK1), located on chromosome 1p36, a region frequently deleted in human cancers and mutated in familial forms of PD." (PMID 26504519, 2015). "Recent mechanistic investigations have further illuminated the therapeutic relevance of this pathway in cancer biology.Specifically, PINK1-mediated mitophagy has been demonstrated to sustain the survival of drug-tolerant persister cancer cells and is associated with an unfavorable prognosis." (PMID 40855568, 2025). "Mutations in PRKN and PINK1, for instance, may disrupt their tumor-suppressive functions, leading to an enhanced survival mechanism in cancer cells, making them more resistant to treatment." (PMID 39859167, 2025). "Interestingly, this study is the first to show the modulation of PINK1 by cannabinoids as a potential mechanism underlying their cytotoxic effects in cancer." (PMID 40565152, 2025). "Cancer and PD share common mutations in several mitochondrial proteins, e.g., Parkin and PINK1." (PMID 38612708, 2024). "Furthermore, the PINK1-Parkin pathway can trigger a HIF1α-dependent Warburg effect, which is a hallmark of cancer metabolism, by degrading mitochondrial transporters SLC25A37 and SLC25A28." (PMID 38913914, 2024). "Multiple PINK1/Parkin-independent as well as -dependent mitophagy receptors/adaptors have been reported for their cancer-associated roles and functional regulation by ubiquitination in cancer." (PMID 36831455, 2023). "In addition, the inability of cells to divide in PINK1 deficiency causes an increase in chromosomal aberrations, genetic instability, or aneuploidy, which can lead to the development of cancer." (PMID 36830954, 2023). "In this context, the function loss of PINK1/Parkin accelerates the occurrence of pancreatic tumours driven by K‐ras mutant, suggesting that cancer occurrence and progression may be regulated by mitochondrial iron homeostasis." (PMID 36200262, 2022). "We further asked whether the reduced growth of PINK1-deficient tumors is due to increased cell death or decreased cell cycle progression, as both are hallmarks of cancer and involved in Ras-induced tumorigenesis." (PMID 35600352, 2022). "In addition, we also find out that there was a strong association between PINK1 copy number variation and immune infiltrates across cancers." (PMID 33244455, 2020). "In addition, there was a significant association between PINK1 copy number variations and immune infiltrates across cancers." (PMID 33244455, 2020). "Furthermore, PINK1 deficiency reprograms glucose metabolism through HIF1α to maintain cell proliferation and even cancer growth." (PMID 33244455, 2020). "Loss of PINK1 may provide cancer cells metabolic advantages due to reduction of mitochondria-associated oxidative stress." (PMID 31819034, 2019). "However, the inability of cells to divide due to PINK1 deficiency can induce chromosomal aberrations, genetic instability and aneuploidy, which can lead to the progression of many types of cancer." (PMID 30344951, 2018). "Interestingly, the deletion of PINK1 in immortalized mouse embryonic fibroblasts (MEFs) have been found to reduce cancer-associated phenotypes, and this was seen to be reversed by the overexpression of human PINK1." (PMID 30274236, 2018). "Similar to another common PD causal gene PARK2, PINK1 plays a key role in mitochondrial quality control by identifying damaged mitochondrial and targeting them for degradation, important functions dysregulated in neurodegeneration and cancer." (PMID 26504519, 2015). "Heterozygous deletions were prevalent in PRKN, BNIP3L, OPTN, and PINK1, particularly in cancers such as LUSC, ESCA, HNSC, and COAD." (PMID 39859167, 2025). "PINK1, a serine/threonine kinase, acts as a negative regulator of multiple cellular pathways exploited by cancer cells." (PMID 40535571, 2025).